GZMA (granzyme A)
Diseases named in the same sentence as GZMA in open-access papers (continued):
Sharing a sentence is not in itself a finding about the gene and the disease.
tumor (continued). "Comparative analysis between CRC and normal colorectal tissues revealed a marked increase in GZMA within TILs, along with a similar upregulation of GSDMB in tumor cells." (PMID 39030523, 2024). "In comparison to the adjacent non-tumor tissues, the CD56dimCD16hi NK cells within tumors showed a decrease in the expression of cytotoxic effector genes, such as PRF1 and most granzymes (GZMA, GZMH, and GZMM), except for GZMB." (PMID 38552055, 2024). "In the adaptive immune response, TGF-β regulates the production of a variety of cytolytic genes including granzyme A, granzyme B, IFNγ, and FAS ligands, which impair the anti-tumor activity of CD8 + T cells, ultimately leading to pro-tumor TME." (PMID 39065562, 2024). "In both the Axi-cel and Tisa-cel CD8 CAR T cells, >60% of the EM cells expressed both GZMB and GZMA, consistent with the role of TEM cells as memory population with immediate cytolytic capability catalyzing anti-tumor killing." (PMID 38307835, 2024). "Altogether, our comprehensive analyses shed light on the intricate functional roles and regulatory mechanisms of GZMA+IFN-γ+CD8+TILs in the tumor microenvironment, underscoring their potential impact on anti-tumor responses." (PMID 39030523, 2024). "As we previously discovered that CAR T cell killing of NALM6 tumor cells remains unaffected by GZMB inhibition and FasL blocking, we next investigated the contribution of GZMA in CAR T-mediated killing." (PMID 38307835, 2024). "The CD56dimCD16hi subsets of NK cells within the tumor tissue showed lower expression levels of cytotoxic genes like PRF1, GZMB, GZMA, GZMH, and GZMK compared to normal tissues." (PMID 38552055, 2024). "This activation further stimulates these CD8+TILs to secrete increased amounts of GZMA and IFN-γ, thereby enhancing their cytotoxic effects on tumor cells and forming a positive feedback loop." (PMID 39030523, 2024). "Overall, the GzmA-GSDMB and GzmB-GSDME pathways play a crucial role in the body's antitumor immune response, offering novel insights for tumor immunotherapy." (PMID 38987821, 2024). "Our results showed that the expression of CXCL9, CXCL10, GZMA, GZMB, PRF1 and IFNG was significantly higher in tumor tissues than in adjacent normal tissues in GC patients." (PMID 39376571, 2024). "We found that GZMA expression was higher in CX3CR1+ CD8+ T cells compared to CX3CR1− CD8+ T cells in both spleen and the tumor while expression of GZMB was equivalent." (PMID 38881188, 2024). "Our results reveal that CD8+TIL co-expressing GZMA and IFN-γ are crucial in shaping the immune microenvironment, particularly affecting tumor cells that express GSDMB." (PMID 39030523, 2024). "Earlier study has already demonstrated that granzyme A can cleave and activate GSDMB, a member of gasdermin protein family in a NLRP3‐dependent manner, then induce tumor cell pyroptosis and mediate tumor immunotherapy." (PMID 37817895, 2023). "The expression level of gene sets related to cytotoxic T cell activation (perforin, granzyme A, and granzyme B), costimulation (CD80 and CD86), and immune checkpoints (LAG3, CTLA4, PD-L1, and PD-1) was found to be increased in the tumor tissue." (PMID 37606040, 2023). "By examining the levels of effector molecules (CD69, CD107a, GZMA, IFN-γ, TNF-α, GZMB, and Perforin-1), we also noticed that the tumor-infiltrating CD8+ T cell effector response was significantly enhanced by Rig-I deficiency." (PMID 36927693, 2023). "Tumor CD8+ cells (representing CD8+ T cells) and CD57+ cells (representing NK cells) downregulated pyroptosis expression percentage, especially GZMA+ and GSDMB+, acting as a protective prognostic predictor clinically." (PMID 37620327, 2023). "Once inside, Granzyme A specifically and effectively cuts the GSDMB protein, leading to the death of the tumor cells through a process known as pyroptosis." (PMID 37077542, 2023).
tumor (continued). "Granzyme A (GzmA) can cleave GSDMB expressed in gastrointestinal epithelial tumors and lead to the pyroptosis of target tumor cells." (PMID 36969233, 2023). "Tumor ROIs in BM-LUAD expressed higher expressions of CD14, CD163, GZMA, BCL-6, BAD, BCLXL, 4-1BB, VISTA, and IDO1." (PMID 37061716, 2023). "Further research has revealed that GZMA interacts with the F2R receptor on the surface of tumor cells, activating the JAK2/STAT1 signaling pathway, inducing tumor cell apoptosis, and T cell-mediated tumor killing." (PMID 37884883, 2023). "Previous reports have shown that when GZMA cleaved GSDMB or GZMB cleaved GSDME, NK cells and CD8(+) T cells directly triggered pyroptosis of tumor cells." (PMID 37221570, 2023). "Diverse studies revealed that the expression of immune-checkpoints (i.e., CTLA-4, PD-1 and PD-L1) and cytolytic activity markers (i.e., GZMA and PFR1) are important to determine the functional status of local anti-tumor immune response." (PMID 37260772, 2023). "PRF1, GZMA, and GZMK, 3 key effector molecules, were shown to be upregulated, and Rg1-pretreated T cells showed a stronger tumor lytic function at different effector: target cell ratios." (PMID 37546705, 2023). "To examine the lytic activity of immune T cells in relation to the 3 metabolic subtypes, we used the average expression levels of GZMA and PRF1 to determine the level of lytic activity exhibited by immune T cells in each patient's tumor." (PMID 36860731, 2023). "Two effector CD4+ T cells, characterized by high expression of either IFNγ and TNF or GZMA and GZMK, showed an anti‐tumour function." (PMID 35184398, 2022). "The results showed that the expression of CD2, SPN, IL18, PTPRC, GZMA, and TLR7 was upregulated in the tumor group compared with the normal group (p < 0.05)." (PMID 36591509, 2022). "To clarify the correlation between 7 PRGs (BTK, CASP5, EEF2K, GZMA, NR1H2, RIPK3, and SDHB) derived from LASSO Cox regression analysis and immune infiltration in COAD, we applied Tumor Immune Estimation Resource (TIMER) database on these genes." (PMID 35912258, 2022). "With correlating gene expression profiles of cytotoxic T lymphocyte (CTL) markers (CD8A, CD8B, GZMA, GZMB, and PRF1) with T-cell characteristics, the TIDE algorithm predicts immunotherapy of tumor patients." (PMID 36618968, 2022). "In a co-culture system, cytotoxic lymphocytes induced pyroptosis in tumor cells and the killing effects resulted from the cleavage of GSDMB by lymphocyte-derived granzyme A." (PMID 36077828, 2022). "We observed that the expression of NKG7, GZMH, GZMA and GZMB in tumor-infiltrating CD8+ CTSW+ cytotoxic cells were significantly increased in female patients, indicating that these T cells have a stronger antitumor cytotoxic effect." (PMID 36172359, 2022). "By contrast, in the merged pan-cancer cohort, SLC3A2 expression was significantly correlated with lower levels of GZMA and INFG, which were cytotoxic molecules that matter in anti-tumor responses." (PMID 35992269, 2022). "GZMA and GZMB were previously reported to be specifically expressed in CD8+ T cells, indicating that PRRS is a signature involving not only tumor cells but also immune cells." (PMID 35990696, 2022). "Granzyme A induces pyroptosis by hydrolyzing GSDMB, which results in tumor cell death, indicating that pyroptosis positively affects the tumor immune response process." (PMID 35311148, 2022). "Aside from caspases, granzyme A has been reported to cleave GSDMB in lymphocytes, and granzyme B was reported to directly cleave GSDME in tumor cells, ultimately contributing to tumor suppression by invoking pyroptosis." (PMID 36093182, 2022). "GZMA expression was rarely detected in tumour tissues in the SEPT5-vector group, and GZMA expression in the SEPT5-KD1 and SEPT5-KD2 groups increased approximately 8-fold and 6-fold, respectively." (PMID 36439885, 2022).
tumor (continued). "Granzyme A, which is released by CTLs and natural killer cells, can directly cleave GSDMB to mediate tumor cell pyroptosis." (PMID 35928454, 2022). "GZMA cleaves and activates GSDMB NT in cancer cells subsequently producing tumor pyroptosis and cancer regression." (PMID 35281099, 2022). "The analysis revealed a downregulation of F2R in the tumor tissues of CESC, KICH, KIRP, LUAD, LUSC, and UCEC, while a low expression of GZMA was observed in COAD, LUAD, LUSC, UCEC, PAAD, and READ." (PMID 35256589, 2022). "For example, cytotoxic T lymphocytes and NK cells express and release granzyme A into targeted tumor cells to cleave and activate GSDMB, leading to tumor cell pyroptosis." (PMID 36077828, 2022). "Similar proportions of CD56dim/CD16+ NK cells isolated from the tumor microenvironment of NSG‐Tg(Hu‐IL15) mice express functional markers CD69, CD8, and NKG2D, and produce granzyme A and granzyme B when compared to NSG mice." (PMID 35959876, 2022). "The immune cytotoxic/effector genes were mainly expressed by T and NK cells, some of which were commonly up‐regulated in the inflammation and tumor regions in the Stereo‐seq slides, including GNLY, GZMA, GZMB, and NKG7." (PMID 35986392, 2022). "Consistent with our results in the database, GZMA, GZMB, IL18, and IRF1 were decreased in tumor tissues than normal tissues." (PMID 35464869, 2022). "It was revealed that the binding of GZMA to the LDPRSFLL motif at the N-terminus of F2R promotes apoptosis via JAK2/STAT1 signaling, which in synergy with the PD-1 mAb therapy led to tumor suppression in both mouse model and HCC patients." (PMID 35256589, 2022). "In summary, three genes in the PRG model (CASP1, CHMP6, and GZMA) is shown to be a protective factor, while the other three genes (CASP4, DHX9, and DFNA5) were defined as tumor-promoting factors." (PMID 34820372, 2021). "The CYT score was defined as the average expression level of two CYT marker genes (GZMA and PRF1) in the tumor." (PMID 34616736, 2021). "The exosomal protein levels of PFN, GzmA, GzmB, and GNLY are deciding factors for the tumor lysis ability of NK-EVs." (PMID 33808645, 2021). "Of the five GSDM gene members, only GSDMD expression showed a positive correlation with CD8+ T cell marker genes (e.g., CD8A, CD8B, PRF1, GZMA, GZMB, and IFNG) in CTLs across all three tumor cohorts." (PMID 34429144, 2021). "We also identified a subtype of proliferative T cells (Cluster 7 with high KI67 expression) which displayed both effector T-cell features (e.g., GZMA) and dysfunctional markers such as LAG3, TIGIT, and PD-1, indicating compromised tumor cytotoxic activity." (PMID 33144684, 2021). "Of note, we focused on three strongly positively related genes in TCGA and METABRIC datasets, including GZMA, IFNG, and PRF1, which played a crucial role in anti-tumor immune of T lymphocytes." (PMID 33407498, 2021). "First, we observed no significant changes in the stroma fraction, cytolytic activity, and PD-1 expression between CNA versus control subgroups in all inquired tumor samples; however, IFNG, GZMA and PD-L1 expression were elevated in mutant (CNA) cancers." (PMID 34598711, 2021). "In line, T cells with clonal expansion expressed GZMA/B, PRF1, INFG, and MIK67, indicating their tumor-reactive and cytotoxic state." (PMID 33686071, 2021). "hetIL-15 directly affects NK, CD8+ and CD4+ T cells within the tumor promoting their proliferation, survival and cytotoxic commitment, with high levels of IFN-γ production and upregulation of GzmA, GzmB and perforin." (PMID 32461349, 2020). "Granzyme A (GZMA) and perforin 1 (PRF1) secreted by cytotoxic T-cells and NK cells are able to kill tumor cells." (PMID 33254149, 2020). "Cytolytic activity score (CYT), defined as the sum of expression of granzyme A (GZMA) and perforin (PRF1), was used to evaluate overall anti-cancer immune cell killing in the tumor microenvironment (25594174)." (PMID 33371179, 2020).
tumor (continued). "Consistent with the cytotoxic activity, Ly6C+CD8+ population from EMT6 tumor-primed mice expressed higher levels of IFNG, GZMA, GZMB, and PRF1 as assessed by qPCR analyses." (PMID 30926774, 2019). "NK cells potently secreted IFNγ, perforin and granzyme A in vitro after contact with GBM cells and abridged tumour mitochondrial function by diminishing both ATP production and maximal respiration." (PMID 31319548, 2019). "The expression of genes related with tumor microenvironment (CD8A, GZMA, and PRF1) can also affect anti-CTLA-4 and anti-PD-1/PD-L1 therapy." (PMID 32793247, 2018). "After binding to MHC class I antigens on tumor cells via T cell receptor, activated CD8+ cytotoxic T cells release granzyme A (GZMA) and perforin (PRF1) to destroy tumor cells." (PMID 28977839, 2017). "In T cell-mediated anti-tumor immunity, CD8+ cytotoxic T cells recognize MHC class I antigens on the tumor cell surface via T cell receptor to trigger the release of granzyme A (GZMA) and perforin (PRF1) to kill tumor cells." (PMID 28977839, 2017). "In the IMCG cohort for example, CD28 and CD3 with aging decreased expression of GZMA and GZMB, proteases important in T cell and NK-cell-mediated tumor cell lysis." (PMID 27760559, 2016). "Negative correlations between the frequencies of IL-10-expressing B cells and the frequencies of granzyme A- and perforin-expressing CD4+ T cells were also observed in tumor-infiltrating cells." (PMID 27136203, 2016). "Indeed, within tumor‐infiltrating NK cells, NKG7—while highly expressed and a strong correlate of cytotoxicity signature—was surpassed by GZMA and PRF1 in terms of correlation with cytotoxicity score." (PMID 40538191, 2025). "Furthermore, trajectory inference revealed that XCL1+ CD8+ T cells probably have strong development ability to other CD8+ T subpopulations, especially for GZMA+ CD8+ T cells, suggesting that probably plays a key role in anti-tumor immunity." (PMID 41426973, 2025). "Our analysis revealed significant correlations between GZMA, GZMB, GZMK and PRF1 expression and cytotoxic T cell infiltrates across various cancer types, underscoring the crucial roles of these genes in modulating the tumor microenvironment." (PMID 40002821, 2025). "For instance, a research report showed that granzyme A (GrA) could cleave gasdermin B (GSDMB, one of members in gasdermin family) to induce pyroptosis, thereby enhancing anti-tumor immunity." (PMID 40761801, 2025). "Opposing its pro‐tumor functions, GSDMB can exhibit pyroptotic activity and an anti‐tumor effect in the context of an activated anti‐tumor immune response, where its activation, mediated by GZMA from cytotoxic lymphocytes, promotes tumor clearance." (PMID 40783818, 2025). "Specifically, granzyme A (GZMA), granzyme B (GZMB), granzyme K (GZMK) and perforin-1 (PRF1) do not only induce apoptosis and modulate immune response within the tumor microenvironment (TME), but also have other diverse roles, such as potentially regulating homeostasis post-infection." (PMID 40002821, 2025). "Based on the importance of GZMA in NALM6 killing, we next wanted to explore whether the same mechanism contributes to killing of SkOV3-CD19 tumor cells." (PMID 38307835, 2024). "Spatial transcriptomics and mIHC analysis revealed that CD8+TILs co-expressing GZMA and IFN-γ may localize near GSDMB-expressing tumor cells, suggesting potential interactions between these cell types." (PMID 39030523, 2024). "While some of most cells have a T helper 2 (Th2) phenotype and tumor-promoting function, the majority of them are highly cytotoxic and are able to exert potent anti-tumor responses via their FASL, TRAIL, and the secretion of granzyme A, B, K, H, and M, and perforin." (PMID 39624236, 2024). "Moreover, CD8+ T cell interacted with tumor cells and CAFs in the high HEC1 expression group by granzyme A (GZMA)—par‐3 family cell polarity regulator (PARD3)." (PMID 39021287, 2024).
tumor (continued). "Conversely, immune activity-related signatures, including PRF1, GNLY, GZMA, GZMB, and interferon regulatory factor 1, play crucial roles in tumor cell recognition and tumoricidal, with connections to extended survival, and identifying responders to anti-PD-1 antibody treatment." (PMID 38956740, 2024). "GZMA is a component of the interferon gamma (IFN-γ) signature, which has been demonstrated to serve as a predictor of response or non-response to anti-PD-1 therapy as part of an immune-related gene expression signature in ten distinct tumor types." (PMID 39596210, 2024). "In addition to GZMB, another serine protease derived from cytotoxic lymphocytes, granzyme A(GZMA), can segment GSDMB and induce pyroptosis in tumor cells." (PMID 38304430, 2024). "Our results indicated that the CD4+ CTL subset expressed PRF1, GZMA, and GZMB, indicating that CD4+ CTLs may induce apoptosis in tumor cells via the release of cytotoxic mediators, especially granzyme B and perforin." (PMID 38077321, 2023). "The t-SNE plotting of transcriptional data indicated that tumor-infiltrating T cells in rejecting Raji tumor were predominantly CD8+ T cells expressing activation and effector molecules such as granzyme A (GZMA) whereas matching splenic T cells were predominantly naive CD4+ T cells." (PMID 37087494, 2023). "Besides the activation through the canonical and apoptotic pathways, lymphocyte-derived granzyme A cleaved GSDMB in human epithelial cells and led to a significant tumor clearance in co-treatment with an anti-PD-1-antibody in a murine tumor model." (PMID 37664463, 2023). "Cytotoxic lymphocyte-derived granzyme A is able to cleave GSDMB and induce tumor cell pyroptosis." (PMID 37635159, 2023). "Furthermore, the expression of both granzyme A and granzyme B was highest in trNK cells and CD8+ TRM cells in the tumor center." (PMID 37448786, 2023). "Additionally, they continued to express cytotoxic effectors (including GZMA, GZMB, GZMH) reflective of their anti-tumor potential." (PMID 38008725, 2023). "Selected genes are reflecting main anti-tumor immune pathways, such as Th1 signaling (IFNG, TBX21, CD8A/B, IL12B, STAT1 and IRF1), Th1 chemoattraction (CXCL9, CXCL10 and CCL5) and cytotoxic functions (GNLY, PRF1, GZMA, GZMB and GZMH)." (PMID 37726776, 2023). "Immune-related genes, such as CD8A, CD8B, GZMA, GZMB, and PRF1, that may indicate the function of tumor-infiltrating CD8 + T cells were considerably enriched in the group receiving combination therapy." (PMID 37777634, 2023). "Using the TCGA and GTEx data, we could learn the expression of five genes of the TEXPM construct, FTL, GZMA, CD14, and NPC2 were highly expressed in tumor tissues, and IER3 was highly expressed in paracancerous tissues." (PMID 37354485, 2023). "Furthermore, GZMA was co-localized with F2R in HepG2 co-cultured with CD3+ T-cells and tumor tissues." (PMID 35256589, 2022). "Notably, the expression levels of 5 PRGs (CASP1, CASP3, CASP6, GSDMB, and GZMA) were lower in both CRC tissues and the high-stage group, suggesting that their potential function as tumor suppressors in CRC tumorigenesis and development." (PMID 35937993, 2022). "Among them, the expression levels of CD8A, CD8B, GZMA, GZMB, and PRF1 were used to evaluate the infiltration levels of tumor cytotoxic T lymphocytes (CTLs), and a high-CTL-infiltration group has been related to significantly prolonged survival time of patients receiving immunotherapy." (PMID 36405701, 2022). "Furthermore, the relationship between the expression of GZMA, PRF1 and tumor purity and immune cells was investigated, which indicated the similar findings." (PMID 35812403, 2022). "Treating iCCA-bearing rats with Protein vaccine alone led to the increase of CTAL4 antibody titers that correlated with the decrease of tumor SUV ratio, indicating regressed tumor burden, along with increased CD8 and granzyme A (GZMA) expression, and decreased PD-L1 expression on tumor cells." (PMID 36341387, 2022).